CASP9 (caspase 9)
Diseases named in the same sentence as CASP9 in open-access papers (continued):
Sharing a sentence is not in itself a finding about the gene and the disease.
osteosarcoma (34 papers, 2010 to 2025). A usually aggressive malignant bone-forming mesenchymal neoplasm, predominantly affecting adolescents and young adults. "Increased levels of cleaved caspase-3 and cleaved caspase-9 in TF3-treated osteosarcoma cells further suggest that TF3 induces apoptosis in these cells." (PMID 40535821, 2025). "Western blotting revealed that TF3 upregulated the expression of cleaved caspase-3 and cleaved caspase-9 in osteosarcoma cells." (PMID 40535821, 2025). "The treatment upregulated cleaved caspase-3, cleaved caspase-9, phosphorylated H2Ax, Bax, Bak1, and cytochrome c, while downregulating survivin and Mcl-1 in osteosarcoma cells." (PMID 40535821, 2025). "In osteosarcoma, BCA inhibited the growth of osteosarcoma cells by activating caspase 9 and caspase 3 and by increasing the ratio of Bax:Bcl-2/Bcl-XL." (PMID 37111591, 2023). "Treatment with 5-MOP induced a concentration-dependent rise in the number of osteosarcoma cells with active caspase-9." (PMID 37958539, 2023). "We showed that miR-342-5p also had anti-apoptotic effects on the three osteosarcoma cell lines by reducing pro-caspase-9 protein expression (by approximately 3-fold)." (PMID 35337159, 2022). "In the three osteosarcoma cell lines, miR-342-5p induced a strong decrease in pro-caspase-9 protein expression (47 kDa; by 3.3-fold in HOS and MG-63 cells and by 2.5-fold in SaOS-2 cells)." (PMID 35337159, 2022). "While there are no similar results for 5-HMF, aKG, and the combination thereof are available in the literature, the inactivation of caspase-9 with aKG was measured in osteosarcoma cells." (PMID 34829675, 2021). "Results demonstrated that miR-128 knockdown effectively induced osteosarcoma cell apoptosis via decreasing caspase-3 and caspase-9 and arrested Mg63 cells at G2/M phase via inhibition of cyclin D1 and cyclin E2." (PMID 33472642, 2021). "Knockdown of ClC-5 significantly induced osteosarcoma cell apoptosis and increased the release of cytochrome c from mitochondria to cytosol, concomitantly with cleavage of caspase-9, caspase-3, and PARP." (PMID 33614474, 2020). "A recent study has found that the overexpression of p-Smad2, p-Smad3, and Smad4 increased caspase 3 and caspase 9 activation in osteosarcoma cells." (PMID 32126993, 2020). "Western blot analysis indicated that the expression levels of caspase-3 and caspase-9 were significantly increased, suggesting that zinc inhibited the growth and promoted the apoptosis of osteosarcoma cells." (PMID 32075661, 2020). "It has been reported that NC inhibited cell proliferation and induced apoptosis via the upregulation of cleaved caspase-3, cleaved caspase-9, and Bax and the downregulation of Bcl-2 in osteosarcoma cells." (PMID 30847386, 2019). "According to the western blot results, bcl-2, cox-2, and fak were down-regulated whereas caspase-3, caspase-9, p-53, nf-kb, and bax were upregulated in osteosarcoma cells in response to CC/Se-HAp nanoparticles treatment as compared to control." (PMID 31263675, 2019). "According to molecular docking results, angelicin could bind freely to the hub targets, and the hub targets BAX, BRIC2, BCL2, and Casp9 may be effective targets by which angelicin affects osteosarcoma cells." (PMID 37301545, 2023). "However, the contribution of mitochondria to apoptosis induction in MG63 osteosarcoma cell lines, as indicated by the activation of caspase 9 and caspase 3, remains coherent." (PMID 36498999, 2022). "In this report, we showed that Licochalcone A treatment induced cleaved-caspase 8 and caspase 3, but decreased the levels of Bax and cleaved-caspase 9, indicating that Licochalcone A triggers apoptosis that mediated by the extrinsic pathways in osteosarcoma cell lines." (PMID 31269698, 2019). "Taken together, these results suggest that I3C may induce apoptosis in osteosarcoma cells through caspase-3-, caspase-7-, and caspase-9-mediated mechanisms." (PMID 30627573, 2018).
osteosarcoma (continued). "To identify the underlying molecular mechanisms, we used western blotting to analyze the levels of Bcl-2, Bax, p-Akt, cleaved caspase-3, and cleaved caspase-9, which are very important in the regulation of apoptosis in osteosarcoma cells following cisplatin treatment." (PMID 29731768, 2018). "Moreover, JPH203 activated the mitochondria-dependent apoptotic signaling pathway by upregulating pro-apoptotic factors, such as Bad, Bax, and Bak, and the active form of caspase-9, and downregulating anti-apoptotic factors, such as Bcl-2 and Bcl-xL in human osteosarcoma Saos2 cells." (PMID 31601917, 2019). "Besides, honokiol treatment decreased the S and G2/M populations, increased the number of cells at G0/G1, and honokiol-induced apoptosis in osteosarcoma cells through the mitochondria dysfunction leading to activate caspase-9 and involves a caspase-3-mediated mechanism." (PMID 29410403, 2018). "Measurement of caspase-3 and caspase-9 activities further confirmed that silencing BMI-1 expression could enhance cisplatin-induced apoptosis, further explaining clearly the signaling pathway of cisplatin-induced apoptosis in osteosarcoma." (PMID 21311599, 2011). "In this study, the expression levels of activated caspase-3, caspase-7, caspase-9, cleaved PARP, Bcl-2 and Bcl-xl were detected by Western blotting to study the mechanism by which aloin promotes osteosarcoma apoptosis." (PMID 34819120, 2021). "The effect of ClC-5 downregulation on osteosarcoma cell apoptosis and viability was abolished by caspase-3 and caspase-9 inhibitors, but not caspase-8 inhibitor." (PMID 33614474, 2020). "The pro-apoptotic factor cytochrome C has its own tendency to enlarge the mitochondrial-dependent pathway to stimulate caspase-9 and downstream effector caspase-3 cleavage and to then carry on PARP cleavage to MSP-4-induced apoptosis of osteosarcoma MG63 cells." (PMID 29301308, 2018). "In our study, TERT significantly inhibited caspase-3 activity in osteosarcoma cells, but exerted no obvious effects on caspase-9 activity (data not shown)." (PMID 28765565, 2017). "SNHG20 is up-regulated in osteosarcoma tissues and cells and knockdown of SNHG20 up-regulates the expression of apoptosis-related protein Bax, decreases the expression of Bcl-2, inhibits the activity of caspase-3 and caspase-9, and promotes the apoptosis of osteosarcoma cells." (PMID 30744670, 2019). "Moreover, OLE and the combined treatment also obviously caused the upregulation of cleaved caspase-9 and the downregulation of Bcl-2, whereas DDP alone only slightly increased the activation of caspase-9 in 143B and U-2OS cells and did not alter the expression of Bcl-2 in any osteosarcoma cells." (PMID 30267330, 2018).
pancreatic cancer (33 papers, 2003 to 2025). "Additionally, the regulatory effect of theAkt/mTOR pathway might be associated with Bcl-2/caspase-9/c-myc-mediated apoptosis, resulting in cell proliferation in pancreatic cancer cells." (PMID 30429828, 2018). "Studies have found that hydrolyzing arginine with arginine deiminase can induce pancreatic cancer cells to stay in the S phase and up-regulate the expressions of caspase-3 and caspase-9." (PMID 38521793, 2024). "Tephrosin can also promote the apoptosis of PANC-1 and SW1990 pancreatic cancer cells by enhancing the cleavage of Caspase-3, Caspase-9 and PARP." (PMID 35222011, 2021). "Further investigation revealed that orexin-A treatment activates theAkt/mTOR signaling pathway to promote cell proliferation byinhibiting Bcl-2/caspase-9/c-myc-mediated apoptosis in pancreatic cancer cells." (PMID 30429828, 2018). "Consistent with our study results, the expression of PARP, cleaved caspase-3, and caspase-9 was obviously decreased in PHB under-expressing pancreatic cancer cell lines AsPC-1 and MiaPaCa-2, but Bcl-2 was apparently increased." (PMID 30185797, 2018). "qRT-PCR analysis showed that mRNA expression level of Bcl-2 decreased and Bax, Caspase-3, and Caspase-9 increased in a dose-dependent manner after SW1990 pancreatic cancer cells were incubated with 18F-FDG for 24h." (PMID 28881676, 2017). "Our findings also showed that ROS and caspase-9/-2 play regulatory roles in the TRAIL-induced necroptosis of human pancreatic cancer cells." (PMID 26000607, 2015). "Propranolol has been shown to exert growth-suppressive effects on pancreatic cancer cells through the induction of caspase-9-and caspase-3-mediated apoptosis." (PMID 24137229, 2013). "Although, canonically, the activation of the extrinsic pathway (via caspase 8) triggers the induction of the intrinsic pathway, therefore caspase 9 activation, in pancreatic cancer cells, the activation of caspase 9 by HCA seems to be unrelated to the cell death induction." (PMID 36077299, 2022). "Evidence suggests that CTD exerts cytotoxic effects on pancreatic cancer cells by JNK-dependent pathway, as CTD treatment suppressed pancreatic cancer cell proliferation via stimulating caspase-8 and caspase-9, upregulating expression level of Bad, Bid and Bak, while downregulating Bcl-2." (PMID 32707651, 2020). "Therefore, we expected that the stimulation of OX1R can promote cell proliferation through regulating Bcl-2/caspase-9/c-myc-mediated apoptosis in pancreatic cancer." (PMID 30429828, 2018). "To further investigate the possible mechanism of orexin-A-inhibited apoptosis in pancreatic cancer cells, we next examined the expression of Bcl-2, caspase-9, and c-myc proteins, which are key factors in cell apoptosis, in orexin-A-incubated PANC1 cells with or without SB408124 treatment." (PMID 30429828, 2018). "Therefore, our results indicated that orexin-A-mediated cell apoptosis occurs through regulating Bcl-2, caspase-9, and c-myc expression in pancreatic cancer cells." (PMID 30429828, 2018). "Moreover, we also found that inhibition of thestimulation of OX1R can regulate the expression levels of Bcl-2, caspase-9, and c-myc in pancreatic cancer cells." (PMID 30429828, 2018). "In our present study, we confirmed the mitochondrial membrane potential decreased significantly and the protein expression levels of cytochrome C, cleaved Caspase-3, and cleaved Caspase-9 increased significantly in pancreatic cancer cells incubated with 18F-FDG for 24 hours." (PMID 28881676, 2017). "Furthermore, it has been reported that treatment with beta-adrenergic antagonists significantly suppresses the expression of p-ERK, Akt, Bcl-2, and cyclin D1, and induces the activation of caspase-3, caspase-9, and Bax in cultured pancreatic cancer cells." (PMID 25742648, 2015).
pancreatic cancer (continued). "Moreover, cleaved caspase 8 and 3 were seen at 48 h, whereas intrinsic apoptosis markers such as caspase 9 and Bax remained unaffected, in all rfhSP-D-treated pancreatic cancer cell lines as compared to untreated cells, which further confirmed the cell death via Fas-mediated pathway alone." (PMID 29915574, 2018). "Additionally, orexin-A treatment can protect PANC1 cells from apoptosis, whereas inhibition of the stimulation of OX1R results in apoptosis through regulating pancreatic cancer cell expression levels of Bcl-2, caspase-9, and c-myc, which are key apoptotic factors." (PMID 30429828, 2018). "Therefore, this evidence suggested that orexin-A treatment may activate theAkt/mTOR pathway to inhibit apoptosis through regulating Bcl-2/caspase-9/c-myc expression and promote cell proliferation in pancreatic cancer cells." (PMID 30429828, 2018). "We also found that the expression level of Caspase-3 and Caspase-9 mRNA increased at the same time, all of which indicated that the endogenous mitochondria- mediated signaling pathway plays an important role in positron-induced apoptosis of pancreatic cancer cells." (PMID 28881676, 2017). "We found that with the prolong of effect time of 8 mg/ml SJAMP on the pancreatic cancer cells, YAP, TEAD1, and Survivin expression significantly decreased, but the levels of the Hippo upstream gene, MST1, and Caspase-9 increased." (PMID 28099921, 2017). "We next examined the relationship between caspase-9, -2, and ROS in TRAIL-treated pancreatic cancer cells." (PMID 26000607, 2015). "Indeed, our results demonstrated an increase in activation of caspase-8 and caspase-9, followed by the cleavage of caspase-3 and PARP after the treatment of human pancreatic cancer cells with CSE." (PMID 33922003, 2021). "The pancreatic cancer cell line PaTu 8988t (column 2) showed strong expression of each of the proteins investigated, whereas the cell lines SW 480 and Panc-1 showed only expression of BAX, caspase-8, and caspase-9." (PMID 30686270, 2019). "The results of our previous study provided the evidence that melatonin given to the pancreatic cancer cells PANC-1 activated the pro-apoptotic signal transduction pathway and stimulated the expression of caspase-9, thus activating the mitochondrial pathway of apoptosis." (PMID 28481310, 2017). "Accordingly, gemcitabine and Bmi1 siRNA enhanced active caspase-3, active caspase-9 and cleaved poly (ADP-ribose) polymerase-1 in pancreatic cancer cells, and these enhancements could be also suppressed by NAC treatment." (PMID 27177084, 2016). "In support of our assumption, RNAi-mediated knockdown of S100A4 has been reported to block cell growth and motility, and to induce apoptosis in the human pancreatic cancer cell lines BxPC-3, PANC-1 and MIA PaCa-2 via activation of pro-apoptotic signaling proteins including caspase-3, and caspase-9." (PMID 26138287, 2015).
cervical carcinoma (28 papers, 2010 to 2025). A carcinoma arising from either the exocervical squamous epithelium or the endocervical glandular epithelium. "This causes the activation of the caspase-9/caspase-3 cascade, causing apoptosis of cervical cancer cells." (PMID 32986355, 2020). "It has been proven that caspase 9 is the activator of other caspases and therefore mediates the apoptosis in several cancer types such as cervical cancer." (PMID 32782438, 2020). "TMS-TMF-4f increased cleaved PARP, caspase-3, caspase-8, and caspase-9 in a concentration-dependent manner in human cervical cancer cells." (PMID 31816985, 2019). "Activation of caspase-9 is mediated by the Apaf-1 apoptosome and caspase-9 induces apoptosis through caspase-3 activation in human cervical cancer cells." (PMID 30627573, 2018). "We found that α-mangostin effectively inhibited cell viability, resulted in loss of mitochondrial membrane potential (MMP), release of cytochrome C, increase of Bax, decrease of Bcl-2, and activation of caspase-9/caspase-3 cascade in cervical cancer cells." (PMID 28537893, 2017). "The present study has revealed that α-mangostin enhances ROS production and results in activation of the ASK/p38 signaling pathway and mitochondria-dependent caspase-9/caspase-3 cascade, leading to induction of apoptotic cell death in cervical cancer cells." (PMID 28537893, 2017). "The activation of caspase-3, caspase-9 and down regulation of Bcl-2 mRNA demonstrated mitochondrial mediated apoptosis in cervical cancer cells, thus delineating brittle star saponin fraction as potent anticancer agents in the treatment of cervical cancer." (PMID 28496480, 2017). "The activity of caspase 3, caspase 8, and caspase 9 was decreased in cisplatin-resistant cervical cancer cells." (PMID 28842515, 2017). "To analyze the Caspase-dependent apoptosis induced by DEPTOR silencing in cervical cancer cells, we assessed levels of Caspase-9 and Caspase-3 by immunoblotting." (PMID 26992219, 2016). "Several genes involved in pathways altered in early stages of cervical cancer, such as CASP9 and EGR2 involved in apoptosis and MYC-N, CCNA and RhoA involved in cell proliferation, were altered by HPV16 E2 expression." (PMID 21599968, 2011). "To further explore whether TAZ could regulate the expression of mitochondria-derived Caspases, which are important factors in the apoptosis pathway, we detected the levels of Cleaved Caspase 9 and Cleaved Caspase 3 proteins in distinct types of cervical cancer cells via Western blot." (PMID 28489874, 2017). "The enhancement of caspase-9 and caspase-3 production suggests that GACP holds potential as an anticancer agent, particularly for the treatment of cervical cancer." (PMID 37767520, 2023). "CAR mediates the activation of caspase-9 and -3 (intrinsic pathway) and caspase-8 (extrinsic pathway) accompanied by the cleavage of PARP in cervical cancer cells." (PMID 36712982, 2022). "Supporting our results, previous studies have shown that AM induces apoptotic cell death by increasing Bax and cytochrome c release, decreasing Bcl-2, and activating caspase-9/caspase-3 cascade as well as the ASKI/MKK3/6/p38 signaling pathway in HeLa and SiHa cervical cancer cells." (PMID 36769377, 2023). "The results indicate that GRg5, in combination with PTX, augments Bax and cleaved caspase-9 and simultaneously diminishes Bcl-2, which confirms the efficacy of GRg5 aided PTX to control PTX resistant cervical cancer cells through a mitochondrial-mediated intrinsic apoptotic pathway." (PMID 35885925, 2022). "In the case of cervical cancer, studies with primary cultures from tumors and cell lines have demonstrated the functional expression of the P2X7R that mediates apoptosis with an expression increase of caspase-3 and caspase-9." (PMID 31249523, 2019). "Furthermore, the Cleaved Caspase 9 and Cleaved Caspase 3 were down-regulated by TAZ in cervical cancer cells." (PMID 28489874, 2017).
cervical carcinoma (continued). "In the present study, we found that LicA substantially increased the levels of LC3-II, in addition to increasing caspase-3, caspase-9, and PARP cleavage, in cervical cancer cells, all of which suggested that LicA induces both apoptosis and autophagy in these cells." (PMID 26311737, 2015).